IGF1 (insulin like growth factor 1)
Diseases named in the same sentence as IGF1 in open-access papers (continued):
Sharing a sentence is not in itself a finding about the gene and the disease.
breast cancer (continued). "Instead, studies with breast cancer cell lines have yielded much evidence for this two-way cross talk between estrogen and the IGF-1 pathway." (PMID 25040542, 2014). "In summary, this study demonstrates that IGF-1, which is significantly involved in poor prognosis and outcome in women with breast cancer, upregulates Cyr61 through both the MAPK and PI3K/Akt pathways resulting in cell invasion and growth." (PMID 25062088, 2014). "Breast cancer cells with abnormalities in the IGF-pathway showed IGF-1-mediated suppression of apoptosis and subsequently, were more resistant to doxorubicin and paclitaxel." (PMID 24396438, 2014). "Higher insulin-like growth factor (IGF)-1 and lower IGF binding protein (BP)-3 levels have been associated with higher commoncancer risk, including breast cancer." (PMID 25285521, 2014). "Obesity-related effects on insulin levels and the insulin-like growth factor-1 (IGF-1) axis, some adipokines, and inflammatory cytokines also stimulate breast cancer growth and metastasis, both directly and most probably by enhanced angiogenesis." (PMID 24693452, 2014). "Insulin-like growth factor (IGF) binding protein 3 (IGFBP3) is a major carrier of IGF1 and IGF2 in circulation and IGFBP3 levels are reduced in breast cancer patients, giving rise to higher free IGF1 levels and poor prognosis." (PMID 24534923, 2014). "IGF-1 has clearly been shown to be a potent mitogen in both in vitro and in vivo studies capable of breast cell tumorogenesis and breast cancer cell progression." (PMID 25062088, 2014). "Treatment of breast cancer cells with insulin like growth factor-1 (IGF-1), which activated the PI3K pathway resulted in decreased ER expression." (PMID 25051360, 2014). "Hyperinsulinemia amplifies bioavailablity of insulin like growth factor-1 (IGF-1), which together with insulin are known to promote human breast cancer." (PMID 24911052, 2014). "Although the IGF-1/IGF-1R pathway seems to be important in breast cancer, its role in BCSCs remains to be delineated." (PMID 23663564, 2013). "It has proposed an autocrine signaling function as breast cancer are able to produce and secrete IGF-1 and leptin and express cell surface receptors for both ligands." (PMID 24340245, 2013). "Based on studies of endometrial and breast cancer tissue, we can observe a profound and complex crosslink between estrogen, progesterone, insulin or IGF-1 and its receptors." (PMID 24308813, 2013). "Abundant data garnered from clinical studies have confirmed that increased serum IGF-1 and/or decreased IGFBP-3 levels are risk factors for growth, invasion and metastasis of many malignancies, including NSCLC, colon and breast cancer." (PMID 23833672, 2013). "Paracrine signaling has mainly been described for breast cancer, where stromal cells have been shown to produce IGF-1 and IGF-2." (PMID 23525758, 2013). "The expression of IGF-1 in breast cancer tissues and serum of breast cancer patients was significantly higher than those in normal healthy individuals." (PMID 23663564, 2013). "In chronic toxicity studies with recombinant human IGF-1, supra-pharmacological doses increased the incidence of mammary carcinoma and pheochromocytoma in female and male rats." (PMID 24260289, 2013). "Recently, we reported that STAT5b regulates the transactivation of cyclin D1 and IGF-1 upon hypoxia stimulation in breast cancer cells." (PMID 22485142, 2012). "Using this assay, we performed a detailed pharmacological analysis of PIP3 production induced by IGF1, insulin and insulin analogues in living breast cancer-derived MCF-7 and MDA-MB231 cells." (PMID 22848683, 2012). "In mammary cancer cells, lycopene treatment markedly reduced IGF-1 stimulation of both tyrosine phosphorylation of insulin receptor substrate-1 and the DNA binding capacity of the activator 1 (AP-1) transcription factor." (PMID 22418926, 2012).
breast cancer (continued). "High circulating IGF-1 concentrations and low blood IGF binding protein concentrations are risk factors for several types of cancer including breast cancer." (PMID 22662119, 2012). "High circulating IGF-1 concentrations and low blood IGF binding protein concentrations are a risk factor for several types of cancer including breast cancer." (PMID 22662119, 2012). "Dusp14 is a MAPK phosphatase responsible for dephosphorylating ERK, JNK, and p38, and thus, of extreme importance as a downstream signal in the IGF-1 pathway in regulating mammary tumor growth." (PMID 23342276, 2012). "The parental R1 was shown to partially inhibit the binding of 125I-labeled IGF-1 (125I-IGF-1) to the human breast cancer cell line MCF-7L (a subline of MCF7) comparable to MAB391." (PMID 22952934, 2012). "Taken together, these data give new insights into mechanisms governing IGF-1 signaling in breast cancer." (PMID 23226206, 2012). "Adaptations to the model include the addition of breast cancer therapies and their potential influence on biomarkers as well as the addition of insulin-like growth factor 1 (IGF-1) and IGF binding protein 3 (IGFBP-3)." (PMID 23153358, 2012). "It is known that IGF-1 stimulates mitosis and inhibits apoptosis, playing a significant role in signaling pathways involved in the pathogenesis of breast cancer." (PMID 23057841, 2012). "Because oxidative stress can be an upstream effector of caspase activation, and is suppressed by IGF-1 in breast cancer cells, we further determined the levels of ROS in cells undergoing the hormonal treatments in medium supplemented with or devoid of IGF-1." (PMID 22429491, 2012). "In this study we set out to define miRNAs that are regulated by IGF-1 through signaling in the ER+ MCF-7 breast cancer cell line." (PMID 23226206, 2012). "Here we demonstrate for the first time a role for IGF-1 signaling in the regulation of miRNAs in the ER+ MCF-7 breast cancer cell line." (PMID 23226206, 2012). "The effects of IGF-1 on oncogenic and tumor suppressive miRNAs in ER+ breast carcinomas have yet to be elucidated." (PMID 23226206, 2012). "The effects of IGF-1 induced signaling cascades on miRNA expression in estrogen receptor (ER) positive (+) breast carcinomas has yet to be evaluated." (PMID 23226206, 2012). "In breast carcinomas, increased levels of insulin-like growth factor 1 (IGF-1) can act as a mitogen to augment tumorigenesis through the regulation of MAPK and AKT signaling pathways." (PMID 23226206, 2012). "IGF-1 signaling ultimately induces the activation of latent TGF-β1 leading to EMT in a breast cancer cell line." (PMID 21535875, 2011). "This reiterates the importance of IGF-1 mediated protease activation, and the downstream consequences of increased IGF-1 signaling in cell migration, invasion, and breast cancer." (PMID 21535875, 2011). "While much is known about TGF-β signaling in comparison, the mechanism of TGF-β activation, and its relationship to IGF-1 in breast cancer metastasis, is poorly understood." (PMID 21535875, 2011). "Altogether, these results strengthen the inverse relationship between PAX2 activity and cellular invasion and identify IGF-1 as a negative regulator of PAX2 activity in luminal breast cancer cells." (PMID 22168360, 2011). "MCF-7 breast cancer cells treated with recombinant IGF-1 were assayed for metalloproteinase activity and invasiveness through a matrigel coated transwell invasion chamber." (PMID 21535875, 2011). "For instance, both the IGF-1/insulin receptor families and the C/EBPβ isoforms play important roles in cellular processes that regulate mammary development and breast cancer such as cell cycle control, proliferation, and differentiation." (PMID 21854628, 2011). "It is important to remember that IGF-1 is much more mitogenic than insulin, and an insulin concentration 100 times that of IGF-1 was needed to elicit equivalent breast cancer cell growth." (PMID 21773024, 2011).
breast cancer (continued). "Insulin-like growth factor 1 (IGF-1) receptor (IGF-1R) is phosphorylated in all breast cancer subtypes." (PMID 21595894, 2011). "The study demonstrates that PAX2 activation by estradiol is selectively achieved in breast cancer cells of the luminal subtype, via ERα, and identifies IGF-1 as a negative regulator of PAX2 activity in these cells." (PMID 22168360, 2011). "With respect to the positive association between OC use and breast cancer, if mediated through IGF-1, we would expect IGF-1 levels to be higher in current or recent users and/or women who started OC at a younger age." (PMID 21599947, 2011). "Results showed that IGF-1 - a molecule known to be elevated in breast cancer is a regulator of matrix metalloproteinase activity (MMP) and the invasive potential of MCF-7 breast cancer cells." (PMID 21535875, 2011). "We anticipate that CNT-based biosensors will ultimately provide a rapid clinical tool to accurately and inexpensively help define the therapeutic potential of candidate biomarkers, such as IGF-1 for the early detection of breast cancer." (PMID 21888628, 2011). "The OR for breast cancer for women in the highest versus the lowest fifth of IGF1 concentration was 1·28 (95% CI 1·14–1·44; p<0·0001)." (PMID 20472501, 2010). "Even though it is known that the circulating IGF2 concentration is much higher than that of IGF1, there is limited evidence on its mitogenic activity in relation to breast cancer and disease, thus implications of IGF2 on breast cancer risk are inconclusive." (PMID 20302654, 2010). "IGF1 is a mitogen predicted to be involved in the development of several human cancers, including breast cancer." (PMID 20302654, 2010). "In postmenopausal women the findings are less clear and positive association of either IGF1, IGFBP3 or both with breast cancer has been reported while other studies are negative." (PMID 20302654, 2010). "In this study we undertook a collaborative analysis of data from 17 studies to investigate the associations of IGF1 and IGFBP3 with breast-cancer risk." (PMID 20472501, 2010). "Another possible route for IGF1 to affect human breast cancer cells is via its interaction with oestrogen." (PMID 22493645, 2009). "In most breast cancer cell lines IGF1 stimulates ER expression, whilst oestrogen increases the expression of IGF1R." (PMID 22493645, 2009). "Extensive evidence from in vivo and in vitro model systems and human studies supports a major role for the IGF1 signaling pathway in breast cancer pathogenesis." (PMID 19843326, 2009). "Insulin-like growth factors (IGFs) are small potent mitogenic proteins and there is significant evidence that IGF1 promotes breast cancer and plays a role in disease progression." (PMID 19536088, 2009). "In breast cancer, IGF-1 expression is elevated in the serum of patients and the IGF-1R is frequently over-expressed and is a prognostic indicator of tumor recurrence and reduced patient survival." (PMID 19534786, 2009). "It is presumed that estrogen and insulin/IGF-1 regulate c-Myc and cyclin D1 during breast cancer cell proliferation." (PMID 19865540, 2009). "Both oestrogen and IGF1 are potent mitogens for most human breast cancer cell lines, interaction between their receptors is likely to be involved in modulating the progress of mammary carcinogenesis." (PMID 22493645, 2009). "We anticipated that wild-type IGFBP4 would be unable to block IGF1 activity in 4T1.2 mammary tumours in vivo because of the presence of active PAPP-A in mammary tissue." (PMID 19536088, 2009). "Progestin stimulation prior to IGF-1 treatment of PR+ breast carcinoma cells upregulates IRS-2 expression levels and tyrosine phosphorylation, thereby enhancing downstream IRS-2-dependent signals." (PMID 19534786, 2009). "IRS-1 is the predominant IRS family member that is activated by IGF-1 in well-differentiated estrogen receptor positive (ER+) human breast carcinoma cell lines." (PMID 19534786, 2009).
breast cancer (continued). "Several studies have since demonstrated that IGF-1 promotes cell motility and invasion in human breast carcinoma cell lines and mouse mammary tumor cells that signal preferentially through IRS-2, but not in cell lines that express only IRS-1." (PMID 19534786, 2009). "Numerous recent epidemiologic studies have begun to examine variation in the genes encoding IGF1, IGFBP1, and IGFBP3 in relation to breast cancer risk." (PMID 18596909, 2008). "Other investigators have found that in MCF-7 breast cancer cells, insulin-like growth factor-1 increases both activity and expression of human ether-a-go-go potassium channels by stimulation of Akt." (PMID 21655370, 2008). "Our study is by far the largest to examine genetic variation in the IGF1, IGFBP1, and IGFBP3 genes in relation to both circulating IGF-I and IGFBP-3 levels and breast cancer risk." (PMID 18596909, 2008). "Other studies have primarily examined individual variants in IGF1, IGFBP1, or IGFBP3 in relation to breast cancer with mixed results." (PMID 18596909, 2008). "No consistent interactions were observed among variants in the IGF1, IGFBP1, and IGFBP3 genes with any of the following: first-degree family history of breast cancer, ever oral contraceptive use, use of postmenopausal hormones, and BMI (<25, 25-<30, 30+)." (PMID 18596909, 2008). "Our findings are consistent with two previous studies that comprehensively examined the role of IGF1, IGFBP1, and IGFBP3 genetic variation in relation to circulating IGF-I and IGFBP-3 levels and breast cancer risk." (PMID 18596909, 2008). "Further, we recognised that IGF-1 stimulated potassium-chloride cotransporters, which were required for invasion and proliferation of cervical cancer, ovarian cancer and breast cancer cells." (PMID 18781172, 2008). "We comprehensively examined the association between common genetic variation in the IGF1, IGFBP1, and IGFBP3 genes in relation to circulating IGF-I and IGFBP-3 levels and breast cancer risk within the NCI Breast and Prostate Cancer Cohort Consortium (BPC3)." (PMID 18596909, 2008). "Estrogen and insulin-like growth factor-1 (IGF-1) play important roles in mammary gland development and breast cancer." (PMID 17201918, 2007). "Four hundred and three breast cancer patients diagnosed in Lund, Sweden, at age 25–99 years were genotyped for the IGF1 CA-repeat length using fragment analysis." (PMID 17311016, 2007). "If confirmed, our data suggest that IGF1 genotyping should be considered in all women with multiple pregnancies to determine the optimal start age for breast cancer screening." (PMID 17311016, 2007). "There was a highly significant interaction between multiparity and IGF1-19/-19 on age at breast cancer diagnosis (P=0.007)." (PMID 17311016, 2007). "It was noteworthy that only one of the young breast cancer patients with the IGF1-19/-19 genotype had less than two children." (PMID 17311016, 2007). "The interaction between two or more recognised pregnancies and the IGF1-19/-19 genotype on the age at breast cancer diagnosis was still significant (P=0.02)." (PMID 17311016, 2007). "In multiparous patients with the IGF1-19/-19 genotype, the mean age at breast cancer diagnosis was 9.2 years earlier compared with uniparous or nulliparous patients (P=0.006)." (PMID 17311016, 2007). "Multiparous patients with the IGF1-19/-19 genotype had a 9.2-year earlier age at breast cancer diagnosis compared with nulliparous or uniparous patients with the same genotype." (PMID 17311016, 2007). "The main finding of this study was that there was a highly significant interaction between multiparity and the IGF1-19/-19 genotype on age at breast cancer diagnosis." (PMID 17311016, 2007). "We have performed a large-scale association study, nested in the EPIC cohort, to assess the role of genetic variation of IGF1 and of the genes encoding the major IGF-I binding proteins on risk of breast cancer and on circulating levels of IGF-I and IGFBP-3." (PMID 16404426, 2006).
breast cancer (continued). "IGFBP-1 is known to neutralise the actions of IGF-1, but in addition, it exerts independent actions as it inhibits breast cancer cell motility and growth by itself." (PMID 15846300, 2005). "The goal of this study was to elucidate the relationships between IGF1 genotype, early-onset breast cancer, breast volume, circulating IGF-1 levels and OC use in a prospective cohort of 258 healthy women ⩽40 years old from high-risk breast cancer families." (PMID 15756256, 2005). "In particular, oestrogen and IGF-1 have been shown to stimulate the phosphorylation of Akt and induce its kinase activity in breast cancer cells." (PMID 16168126, 2005). "Studies have shown that both insulin and IGF-1 exert a mitogenic effect by stimulating cell proliferation and inhibiting apoptosis of breast cancer cells." (PMID 16168130, 2005). "It is possible that the decrease in IGF-1 levels in parous women accounts partially for the protective effect of parity against breast cancer." (PMID 15756256, 2005). "CCN6-rich medium induces a decrease in IGF-1-stimulated IGF-1R phosphorylation in breast cancer cells, and then results in an inhibition of cellular proliferation." (PMID 16457688, 2005). "We have hypothesised that the elevation in IGF-1 levels, brought on by pregnancy or exogenous hormones (in particular teenage OC use) in the context of an absent 19-repeat allele, may play an important role in the pathogenesis of early-onset breast cancer and lead to an increase in breast volume." (PMID 15756256, 2005). "Over-expression of certain members of the IGF system increased sensitivity to IGF1 signaling in breast cancer cells leading to increased cell proliferation." (PMID 15471544, 2004). "In accordance with the suggestion from previous epidemiological and experimental studies, our results support further investigation of the role of IGF1 in breast cancer aetiology." (PMID 12610514, 2003). "In our MEC sample plasma IGF1 levels were thus high among the three racial/ethnic groups with high breast cancer rates and lowest among the racial/ethnic group with the lowest breast cancer rates." (PMID 12610514, 2003). "Insulin-like growth factor 1 (IGF-1) plasma level was assayed in 60 breast cancer patients undergoing six courses of adjuvant chemotherapy." (PMID 9635846, 1998). "Breast cancer patients usually have elevated levels of GH and IGF-1 in their circulation." (PMID 41700740, 2026). "Additionally, animal studies have demonstrated that exposure to high levels of IGF-1 enhances breast cancer growth and metastasis." (PMID 41310487, 2025). "Moreover, IGF-1 treatment promotes system xc(−) expression and glutamate export in several human breast cancer cell lines." (PMID 39433211, 2025). "Similarly, basal and maximal ECAR are increased with IGF-1 treatment in human breast cancer cells and with IGF-1 overexpression in rat dorsal root ganglion (DRG) neurons." (PMID 39433211, 2025). "The IGF-1 bioregulation system is essential for the normal development and function of the mammary gland, and it is also involved, along with the estrogens, in breast development, as well as in breast cancer." (PMID 41153350, 2025). "In another trial, the authors investigated the effects of melatonin on breast cancer markers [insulin-like growth factor 1 (IGF-1), estradiol, insulin-like growth factor-binding protein-3 (IGFBP-3), and IGF-1/IGFBP-3 ratio] in postmenopausal breast cancer survivors." (PMID 40001911, 2025). "By modulating the GH/IGF-1 axis, somatostatin analogs might counteract pro-survival and pro-proliferative signals in early mammary carcinogenesis, rendering them candidates for preventing breast cancer—particularly in individuals with elevated baseline IGF-1." (PMID 40243654, 2025).